IL17A (interleukin 17A)
Diseases named in the same sentence as IL17A in open-access papers (continued):
Sharing a sentence is not in itself a finding about the gene and the disease.
psoriasis (continued). "Given the convincing evidence for a direct contribution of IL-23 to psoriasis, we concentrated on a reductionist model that relies on intradermal injections of IL-23 alone, in which the dermatitis depends on the subsequent expression of IL-22 and IL-17A (refs 11, 16, 17, 38)." (PMID 27982014, 2016). "Resveratrol ameliorates psoriasis, and changes expression of retinoic acid stimulated genes, IL-17 signalling pathways, IL-17A and IL-19 mRNA levels in a beneficial manner, which suggests resveratrol, might have a role in the treatment of psoriasis and should be explored further in a human setting." (PMID 25965695, 2015). "In fact, in a mouse model of imiquimod-induced psoriasis-like inflammation, topical curcumin was demonstrated to improve the skin lesions with an effect comparable to that of clobetasol and to significantly decrease the cutaneous levels of IL-17A, IL-17F, IL-22, IL-1β, IL-6, and TNF-α mRNA." (PMID 26090395, 2015). "Several anti-IL-17A inhibitors have been shown in vitro and in vivo to reduce the release of innate immune effectors and are currently being investigated in clinical trials for the treatment of several inflammatory conditions such as rheumatoid arthritis, uveitis, and psoriasis (22, –, 24)." (PMID 24692552, 2014). "Here, a digital surface-enhanced Raman spectroscopy (SERS) immunoassay has been developed for multiplex detection of IL-17A, IL-22, IL-23 and TNF in punch biopsy skin using psoriasis as a model." (PMID 42124321, 2026). "In psoriasis explants, SHIN1 decreased the expression of Ki67, Keratin 16, and pro-inflammatory cytokines including IL-17A, IL-22, and IFN-γ." (PMID 42103703, 2026). "Brodalumab, a monoclonal antibody binding to IL-17 receptor A and blocking IL-17A, IL-17C, IL-17F, IL-17A/F, and IL-17E (also known as IL-25), got the FDA approval for adult psoriasis in 2017." (PMID 41481132, 2026). "In this study, we investigated serum levels of IL-6, IL-17A, IFN-α, IFN-γ, and TNF-α in patients with psoriasis before and after treatment with brodalumab, all of whom had previously failed therapy with TNF-α inhibitors." (PMID 41516330, 2026). "Bimekizumab, the group’s newest representative, which blocks IL-17A and IL-17F, received FDA approval for the treatment of psoriasis in adults in 2023." (PMID 41481132, 2026). "This prospective study investigated the effects of brodalumab on serum cytokine levels—specifically IL-6, IL-17A, IFN-α, IFN-γ, and TNF-α—and their correlation with disease severity as assessed by Psoriasis Area and Severity Index (PASI)." (PMID 41516330, 2026). "Ixekizumab, also an IL-17A-neutralizing agent, was approved by the FDA for the treatment of psoriasis in adults in 2016, and in 2020 in people aged 6–18." (PMID 41481132, 2026). "At the same time, M1 secretion of TNF-α and IL-18 and other pro-inflammatory factors promote Th1/Th17 cells to secrete IL-17A, IFN-γ and IL-21 and other inflammatory factors, which aggravates the inflammatory response of psoriasis." (PMID 40362523, 2025). "The in vitro models primarily involved HaCaT keratinocytes stimulated by psoriasis serum-derived exosomes, IL-17A, or TNF-α combined with IL-17A to mimic psoriatic conditions." (PMID 41007656, 2025). "CXCL8 and CXCL13 have already been implicated in early disease stages, with CXCL8 upregulated in mild psoriasis and CXCL13 expressed by lesion-infiltrating T cells, correlating with IL-17A levels." (PMID 40943056, 2025). "Proteins related to the central disease‐driving pathways of psoriasis, namely the TH1 (CCL3, CCL4, CXCL9, CXCL10, CXCL11, TNFα) and TH17 pathway (CXCL1, CCL20, IL‐17A, IL‐12B) were found elevated in lesional skin across both studies." (PMID 40970551, 2025). "Secukinumab, ixekizumab, and bimekizumab are monoclonal antibodies targeting IL17A/IL17RA, which are approved in clinical use to treat psoriasis." (PMID 39959414, 2025).
psoriasis (continued). "Multiple inflammatory mediators and signaling pathways contribute to the pathophysiology of psoriasis, including tumor necrosis factor (TNF), prostaglandin–endoperoxide synthase 2 (PTGS2), and interleukin-17A (IL-17A)." (PMID 41471291, 2025). "In our research, we analyzed how clinical and inflammatory aspects, such as BMI, triglycerides, glycemia, leptin, SII and the cytokines IL-17A and IL-23, influence quality of life as measured by DLQI, in psoriasis patients after one year of treatment." (PMID 40003621, 2025). "Contrarily, after Guselkumab withdrawal, increases in serum levels of IL-17A, IL-17F, and IL-22 lagged behind PASI worsening, indicating they are poor predictors of psoriasis flare-ups." (PMID 40699767, 2025). "IL‐17A is a primary driver of skin pathology in psoriasis, and our results showed that LINC01206 expression is significantly upregulated in both psoriatic lesions and IL‐17A‐stimulated keratinocytes." (PMID 40670887, 2025). "We validate these findings in murine models of wound repair and imiquimod (IMQ)-induced psoriasis-like inflammation where CCR6 and/or IL17A are expressed by epidermal γδ T cells in vivo." (PMID 40073267, 2025). "The main types of biologics available for psoriasis treatment include tumor necrosis factor (TNF) inhibitors, interleukin-17A inhibitors, and interleukin-23 inhibitors." (PMID 41179072, 2025). "To further explore the inflammatory cytokines regulated by TP treatment, we extracted serum from the mice and analyzed the expression of inflammatory genes, such as IL-17A, IL-22, IL-23, TNF-α, and IL-6, which were closely related to psoriasis pathogenesis." (PMID 40365308, 2025). "Research has indicated that the inflammasome inhibitor (NLRP2/AIM-3-IN-21) exhibited significant therapeutic potential in psoriasis, and effectively suppressed the expression levels of NLRP3, IL-17A, and AIM2 in psoriatic skin lesion tissues." (PMID 41383588, 2025). "Studies in recent years have confirmed that its pathogenesis shares commonalities with psoriasis, such as both including the involvement of TNF-α and IL-17A." (PMID 41142781, 2025). "Patients with rheumatoid arthritis who developed paradoxical psoriasis under TNF-α inhibitor therapy showed an increase in Th17 cells and IL-17A production." (PMID 41142785, 2025). "Reportedly, allicin directly inhibits the IL-17A/F-induced STAT3/NF-κB and TRAF6/MAPK/NF-κB signaling cascades in keratinocytes, thereby attenuating pro-inflammatory feedback and ameliorating psoriasis-like dermatitis." (PMID 40871078, 2025). "IL-17A increased PCNA expression, which was inhibited by TP, thereby suggesting the involvement of TP in suppressing keratinocyte hyperproliferation in psoriasis." (PMID 40365308, 2025). "The identification of particular cytokine circuits including IL-6, IL-17 A, IL17 F, IL-22, IL-23, and TNF-α,) indicate that these mediators interact with each other, forming a network that is likely initiate psoriasis." (PMID 41254515, 2025). "Cytokines like IL-17A, IL-22, IL-23, and tumor necrosis factor-a (TNF-α) play a role in psoriasis pathogenesis." (PMID 40343294, 2025). "In psoriasis, peripheral neutrophils are elevated, recruited by IL-17E and CXCL8, and release IL-17A and extracellular vesicles, stimulating KCs to produce pro-inflammatory factors, enhance migration, and intensify inflammation." (PMID 40303401, 2025). "IL-33 exerts immunomodulatory effects by suppressing IL-17A expression in CD4+T cells isolated from psoriasis patients, likely through inhibition of STAT3-dependent IL17A transcription." (PMID 40681996, 2025). "This is in agreement with several previous biomarker studies of the PDE4 inhibitor apremilast in psoriasis patients, showing a significant modulation of TH1 and TH17 cytokines involved in the pathogenesis of psoriasis (e.g., IL‐17A/F, IL‐22 and TNFα)." (PMID 40970551, 2025).
psoriasis (continued). "Among numerous cytokines involved in the pathogenesis of psoriasis, TNF-α and IL-17A are particularly significant due to their synergistic effects in amplifying chronic inflammation." (PMID 40892753, 2025). "CD274 (PD-L1), CXCL13, BIRC5, and SMPD3 play the following roles in the IL-17a and IL-23 pathways: CD274 (PD-L1): The IL-17a and IL-23 pathways are closely related to the pathogenesis of autoimmune diseases like psoriasis." (PMID 40557155, 2025). "Multiple genetic associations suggest a causative relationship between Th17-related genes coding for proteins, such as IL-17A, IL-23 and STAT3, and psoriasis." (PMID 39820614, 2025). "Together with IL-17A, TNF-α plays a central role in regulating the expression of cytokines and keratinocyte genes, thereby modulating keratinocyte function in psoriasis." (PMID 40343299, 2025). "The Inhibition of IL-17A and TNF-α was observed to improve the condition of psoriasis and enhance quality of life." (PMID 40892753, 2025). "The infiltration of IL-17A–positive CD4+ T cells, γδ T cells, and neutrophils was observed in the skin at the experimental endpoint and in human psoriasis, suggesting a critical role of the damaged skin–derived immune cells in systemic IL-17A production." (PMID 39919800, 2025). "In a mouse model of psoriasis induced by the Toll-like receptor 7 (TLR7) agonist named imiquimod (IMQ), it was shown that IL-17A-producing Vγ4Vδ4 T cells exhibit similarities, suggesting oligoclonal expansion or a common fetal origin of these cells." (PMID 40276509, 2025). "Monoclonal antibodies such as Bimekizumab, Secukinumab, Ixekizumab, and Brodalumab, which inhibit IL-17A or IL-17RA, have received FDA approval for managing psoriasis and psoriatic arthritis." (PMID 40469524, 2025). "In IMQ-induced psoriasis mice, Lactiplantibacillus plantarum GMNL-77 reduced the proportion of IL-17A+CD4+ T cells and decreased the expression of inflammatory factors such as TNF-α, IL-23, and IL-17A, leading to amelioration of erythematous and scaly lesions." (PMID 41425939, 2025). "HER4 is also expressed in CD4+ T cells from patients with psoriasis, and treatment with HER4 siRNA reduced mouse IL-17A+ CD4+ T cells in vitro and imiquimod-induced dermatitis in vivo." (PMID 38312837, 2024). "In a study that analyzed the effects of punicalagin, the main chemical compound isolated from PG peel, on psoriasis, the authors used the imiquimod-induced psoriasis model in mice, as well as TNF-α- and IL17A-stimulated HaCaT cells." (PMID 38675119, 2024). "Our study demonstrates that HMGB1 can contribute to the pathogenesis of psoriasis by regulating Th17 cell differentiation through the HMGB1‐TLR4‐IL‐23‐RORγt pathway, then promote IL‐17A production and aggravate inflammation process." (PMID 38414294, 2024). "Mice with TPA-induced psoriasis showed increased gene expression of both the Th17 transcription factor, RORC, and Th17-produced cytokines, Il17a, Il17e, Il17f, and Il22, in the ear tissue compared with those in normal mice." (PMID 39765869, 2024). "We analyzed five murine models of psoriasis-like dermatitis based on topical IMQ application and IL-17A overexpression under different promotors, described previously." (PMID 38127137, 2024). "Recent studies have suggested that CBD’s effects on skin diseases such as allergic contact dermatitis, acne, and psoriasis are attributed to the inhibition of pro-inflammatory cytokines such as TNF-α, IL-1β, IL-6, and IL-17A." (PMID 39335596, 2024). "Together, these data demonstrated that transferred DNT migrates to the skin of psoriasis through CCR5 and inhibits IL-17A-producing γδ T cells." (PMID 38566145, 2024). "However, our present study provides further evidence that HMGB1 participates in the pathogenesis of psoriasis, which may exert its regulatory effect on Th17 cell differentiation and IL‐17A production by IL‐23 and TLR4 signaling pathways to amplify its inflammatory effects." (PMID 38414294, 2024).
psoriasis (continued). "A prominent development by Samir Mitragotri’s team involves the creation of NFKBIZ siRNA, which effectively inhibits the expression of aberrant genes and downregulates psoriasis-related signals, including TNF-α and IL-17A." (PMID 39684717, 2024). "A previous report showed that the Th17 family of cytokines (IL-17A and IL-17F) secreted by skin contained infiltrating γδT cells and RORγt+ innate lymphocytes, which promoted the initiation of IMQ-induced psoriasis." (PMID 38444844, 2024). "Biologics targeting IL-17A, IL-23, and TNF-α have been developed and approved for the treatment of psoriasis." (PMID 38893287, 2024). "on skin tissue from a patient with psoriasis and vitiligo comorbidity revealed elevated levels of CD4, CD8, Foxp3, and IL‐17A in the comorbid skin tissue." (PMID 39031921, 2024). "RA inhibits imiquimod-induced psoriasis-like dermatitis in mice by reducing JAK2/Stat3-dependent Th17 cell differentiation and IL-17A production." (PMID 39684446, 2024). "Glycyrrhizin has demonstrated therapeutic potential for psoriasis by alleviating adverse symptoms in an IMQ-induced mouse model, improving the pathological state of skin cells, and inhibiting IL-17A and IFN-γ expression." (PMID 38892253, 2024). "In psoriasis patients, specific immune responses induced by ADAMTSL5 autoantigen are represented primarily by IL-17A-producing CD8+ T cells and directed against melanocytes and surrounding keratinocytes." (PMID 38495872, 2024). "Based on the available evidence regarding the role of IL17 in psoriasis and PSA, four therapeutic agents against IL-17A, IL17F, or its receptor have been developed: secukinumab, ixekizumab, brodalumab, and bimekizumab." (PMID 39459016, 2024). "As for △PASI >0, IXE and SEC, both targeting IL-17A, showed a significant difference in patient outcome (p < 0.05), suggesting that IXE was better than SEC in controlling psoriasis following COVID-19 infection." (PMID 38298734, 2024). "In psoriasis, PD-1+ CD8+ TRM cells preferentially expressed IL-23R and produce IL-17A, while PD-1− CD8+ TRM cells are a source of IFN-γ." (PMID 38642273, 2024). "Recent progress in biological therapies for psoriasis has revealed the fundamental roles of tumour necrosis factor‐α (TNF‐α), interleukin (IL)‐23p19 and IL‐17A axis in pathogenesis." (PMID 39624730, 2024). "Dead Sea climatotherapy (DSC) and biologic therapies, such as the anti-interleukin (IL)-17A targeting drug secukinumab (SEC), are both effective treatments for psoriasis." (PMID 38892277, 2024). "In parallel, we investigated five murine models of psoriasis-like skin disease, based on topical IMQ application and overexpression of IL-17A under different promotors." (PMID 38127137, 2024). "In a clinical trial, endothelial function—measured by flow-mediated dilation (FMD)—exhibited improvement in patients with psoriasis following treatment with inhibitors targeting tumor necrosis factor-alpha (TNF-α) and Interleukin (IL)-17A." (PMID 39519167, 2024). "The results showed that the IL-17A, IL-6, IL-23, and TNF-α levels increased significantly in IMQ-induced mice with psoriasis." (PMID 39062965, 2024). "One of the major unresolved mysteries is that psoriasis lesion often recur in the identical areas after the discontinuation of biologics targeting TNF-α, IL-23 and IL-17A/IL-17RA." (PMID 38347543, 2024). "Given its established role in autoimmunity, IL-17A blocking antibodies, such as secukinumab and ixekizumab, have received U.S. Food and Drug Administration (FDA) approval for the treatment of psoriasis, ankylosing spondylitis (AS), and psoriatic arthritis." (PMID 39906741, 2024). "The use of biologic has enabled the effective treatment of lesions in individuals with moderate to severe psoriasis, with several biologics receiving approval from the FDA, including IL-23 inhibitors, IL-17A inhibitors, and IL-12/23 inhibitors." (PMID 39219794, 2024).
psoriasis (continued). "ACLS4 expression was directly correlated with the Psoriasis Area Severity Index (PASI) score and inflammation factors, such as TNF-α, interleulin-6 (IL-6), interleukin-8 (IL-8), and interleukin-17a (IL-17a)." (PMID 39125810, 2024). "Results indicated that IDG and DXM significantly inhibited the expression of IL-6, IL-17A, MCP-1, and TNF-α in psoriasis-like lesions, with all findings reaching statistical significance, while the effect on IL-13 was not statistically significant." (PMID 39465158, 2024). "HMGB1 can contribute to the pathogenesis of psoriasis by regulating Th17 cell differentiation through HMGB1‐TLR4‐IL‐23‐RORγt pathway, then promotes IL‐17A production and aggravates inflammation process." (PMID 38414294, 2024). "M (IL-23) produce significant quantities of IL-17A, IL-22, and IFN-γ, contributing to the development of psoriasis-like dermatitis in a mouse model." (PMID 39703508, 2024). "As TH17 cells have been described as main contributors for the development of psoriasis pathology, a psoriasis model was induced by treating HSEs with a TH17-derived cytokine mix (IL-17A and IL-22, 30 ng/ml each)." (PMID 38251799, 2024). "Upon stimulation of the skin of patients with psoriasis, CD8(+) CD103(+) CD49a(−) TRM cells in the epidermis appear to be reactivated and initiate IL-17A production." (PMID 39063202, 2024). "They described that improved recovery of the skin was associated with increased IL-17A and TGF-β in the skin of mice treated with BM- or AD-MSCs, and they hypothesized that TGF-β promoted the controlled differentiation of keratinocytes, resulting in the decreased severity of psoriasis." (PMID 39595528, 2024). "In this study, we examined the relationship between IL-17A and TOPK in skin lesions of psoriasis patients and found that TOPK levels were positively correlated with IL-17A levels." (PMID 39090602, 2024). "The combination of TNF-α, IL-1α, IL-17A, IL-22, and OSM (termed as M5) has been shown to induce psoriasis-like changes, including cell inflammation and increased cell proliferation in cultured keratinocytes." (PMID 36999136, 2023). "Th17 cells and their secreted cytokines, such as IL-17A, IL-23, and TNF-α, play a role in a variety of chronic inflammatory illnesses, including psoriasis." (PMID 37643205, 2023). "Lactiplantibacillus plantarum GMNL-77 (2 × 109 CFU/day) has been reported to decrease the proportion of IL-17A+CD4+T cells and reduce IL-23 and IL-17, thus relieving psoriasis." (PMID 37111171, 2023). "Here the authors establish a role for IL-26 in the generation of IL-17A producing Th17 CD4+ T cells and suggest it involves epithelial cross talk in skin lesions of psoriasis patients." (PMID 37391412, 2023). "Herein, we describe that improved recovery of the skin was associated with increased IL-17A and TGF-β in the skin of mice treated with BM or Ad MSC, and we hypothesize that TGF-β promoted the controlled differentiation of keratinocytes, resulting in the decreased severity of psoriasis." (PMID 37373278, 2023). "The LSNs were assessed by the IMQ model accompanied by visual (psoriasis area severity index; PASI), histological, and pro-psoriatic IL-17A evaluations." (PMID 37836750, 2023). "After systemic IL-17A blockade (12 weeks of anti-IL-17A monoclonal antibody injections), the expression of IL17A in the CD161+ T-cell cluster was decreased to zero in psoriasis lesional skin (p < 0.05)." (PMID 37781383, 2023). "For the T17 axis transcriptome, systemic IL-17A blockade depleted 100% of IL17A+ T-cells and 95% of IL17F+ T-cells in psoriasis skin." (PMID 37781383, 2023). "Indeed, the skin thickening in response to psoriasis-like inflammation was not changed in CD200R1-deficient mice despite the reduction in IL-17A, which suggests that there may be an increase in an alternative inflammatory response in these mice." (PMID 36623588, 2023).